AP1B1 (adaptor related protein complex 1 subunit beta 1)
Description:
Subunit of clathrin-associated adaptor protein complex 1 that plays a role in protein sorting in the late-Golgi/trans-Golgi network (TGN) and/or endosomes. The AP complexes mediate both the recruitment of clathrin to membranes and the recognition of sorting signals within the cytosolic tails of transmembrane cargo molecules.
Synonyms: ADTB1; BAM22; CLAPB2; AP105A; KIDAR
Tractability: Small molecule: a structure with a bound ligand is known. Antibody: UniProt places it where antibodies can reach, with medium confidence. PROTAC: ubiquitination databases record sites on it; its protein half-life has been measured.
Gene: Protein-coding gene on chromosome 22 (29,327,680 to 29,388,612, reverse strand). Ensembl gene ENSG00000100280.
Subcellular location: Golgi apparatus; Cytoplasmic vesicle, clathrin- coated vesicle membrane
Subcellular location (Human Protein Atlas): Golgi apparatus; Cytosol; Vesicles
Pathways (Reactome):
Vesicle-mediated transport: Golgi Associated Vesicle Biogenesis; Lysosome Vesicle Biogenesis
Disease: Nef mediated downregulation of MHC class I complex cell surface expression
Immune System: MHC class II antigen presentation
Gene Ontology:
Molecular function: protein binding; protein kinase binding; clathrin binding
Biological process: basolateral protein secretion; melanosome assembly; platelet dense granule organization; receptor-mediated endocytosis; vesicle-mediated transport; intracellular protein transport; protein transport
Cellular component: Golgi apparatus; AP-1 adaptor complex; cytoplasmic vesicle membrane; cytosol; early endosome; Golgi membrane; lysosomal membrane; trans-Golgi network membrane; clathrin adaptor complex; clathrin-coated vesicle membrane; cytoplasmic vesicle; endomembrane system; membrane coat; synaptic vesicle
Genetic constraint (gnomAD): Loss-of-function variants: 33 observed, 92.62 expected, observed/expected ratio (o/e) 0.36, 90% interval 0.27 to 0.48. The upper end of that interval is the gene's LOEUF score, 0.48, which puts it in group 2 of 6, group 1 being the genes least tolerant of losing a copy. Missense variants: 870 observed, 1,172 expected, observed/expected ratio (o/e) 0.74, 90% interval 0.7 to 0.79. Synonymous variants: 479 observed, 492.91 expected, observed/expected ratio (o/e) 0.97, 90% interval 0.9 to 1.05.
Gene-disease validity (ClinGen):
ClinGen rates the evidence that AP1B1 causes each of these diseases.
ichthyosiform erythroderma, corneal involvement, and hearing loss (autosomal recessive): Definitive.
Homologues: Orthologues: macaque AP1B1 (99% identical), pig AP1B1 (98% identical), rat Ap1b1 (98% identical), chimpanzee AP1B1 (97% identical), guinea pig AP1B1 (97% identical), mouse Ap1b1 (96% identical), rabbit AP1B1 (92% identical), dog AP1B1 (92% identical), tropical clawed frog ap1b1 (89% identical), zebrafish ap1b1 (87% identical), Drosophila melanogaster AP-1-2beta (74% identical), Caenorhabditis elegans apb-1 (66% identical). Paralogues in human: AP2B1 (83% identical), AP3B1 (26% identical), AP3B2 (26% identical), AP4B1 (22% identical).
Diseases named in the same sentence as AP1B1 in open-access papers:
AP1B1 is named in the same sentence as 26 diseases in open-access papers, as found by Europe PMC text mining. Sharing a sentence is not in itself a finding about the gene and the disease. The quoted sentences say what the papers report.
MEDNIK syndrome (3 papers, 2020 to 2025). "Indeed, patients with variants in the AP1B1 gene encoding β1 (KIDAR syndrome) display symptoms almost identical to those of MEDNIK syndrome." (PMID 39269494, 2024). "MEDNIK syndrome, also known as “syndrome de Kamouraska” (syndrome from Kamouraska), is a genetic disorder that is caused by mutations in adaptor related protein complex 1 subunit sigma 1 (AP1S1) and beta 1 (AP1B1) genes." (PMID 32306098, 2020). "Mutations in ubiquitously-expressed genes encoding subunits AP1B1 and AP1S1 cause MEDNIK syndrome." (PMID 32306098, 2020). "The only difference between the symptoms of AP1B1-related KIDAR and AP1S1-related MEDNIK syndromes is the presence of ophthalmological problems, such as keratitis and corneal scarring, in KIDAR patients, which have not been reported in MEDNIK patients." (PMID 39269494, 2024).
deafness (2 papers, 2022 to 2023). An inherited or acquired condition characterized by the complete loss of the ability to hear from one or both ears. "The presence of two-point mutations in the AP1B1 gene causes keratisichthyosis-deafness and developmental delay, named KIDAR syndrome." (PMID 37108275, 2023). "In humans, the recessive loss-of-function of AP1B1 variants (β1) causes a multi-organ disorder with clinical manifestations, including ichthyosis, deafness and photophobia." (PMID 37108275, 2023). "Among these genes, AP1B1 has previously been reported to be associated with MEDNIK-like syndrome (intellectual disability, enteropathy, deafness (sensorineural), neuropathy, ichthyosis, and keratodermia), which shows an autosomal recessive inheritance." (PMID 36077416, 2022).
enteropathy (2 papers, 2022 to 2023). "Additionally, recessive loss-of-function variants in AP1B1 cause a multi-organ disorder with clinical manifestations such as enteropathy, hearing impairment, peripheral neuropathy, keratodermia encephalopathy and intellectual disability." (PMID 37108275, 2023).
Intellectual disability (2 papers, 2022 to 2023). "The last two patients displayed intellectual disability, possibly related to AP1B1 gene deletion." (PMID 36077416, 2022). "The absence of loss-of-function mutations in both AP1B1 alleles, besides the gene expression being reduced by half in both patients, could be suggestive of a mild expression of a MEDNIK-like syndrome phenotype, limited to intellectual disability." (PMID 36077416, 2022).
autism spectrum disorder (1 paper, 2017). A spectrum of developmental disorders that includes autism, and Asperger syndrome. "Gene AP1B1 has been correlated with the neural-regulated micro-exon in autism spectrum disorder." (PMID 28792504, 2017).
DiGeorge syndrome (1 paper, 2023). "A 22q11.21 microdeletion encompassing the TBX1, SHANK3, SOX10, AP1B1, FBXO7, MYH9, and SPECC1L genes cause DiGeorge syndrome, which is associated with DD, ID, seizure, and cardiac malformations, with a prevalence of 1 in 4000." (PMID 37189911, 2023).
Ewing sarcoma (1 paper, 2022). A small round cell tumor that lacks morphologic, immunohistochemical, and electron microscopic evidence of neuroectodermal differentiation. "In Ewing sarcoma, disruption of AP1B1, a neighboring gene of EWSR1, has been shown to be caused by bridged chromoplectic rearrangements also fusing EWSR1 and FLI1." (PMID 36232302, 2022).
glioblastoma (1 paper, 2019). The most malignant astrocytic tumor (WHO grade IV). "Identified were five fasting-responsive proteins that overlapped between the lines, including adaptor related protein complex 1 beta 1 subunit (AP1B1), CAPZA2, chaperonin containing TCP1 subunit 5 (CCT5), glioblastoma amplified sequence (GBAS), and 40 S ribosomal protein S21 (RPS21)." (PMID 30931934, 2019). "AP1B1, adaptor related protein complex 1 beta 1 subunit; CAPZA2, F-actin-capping protein subunit alpha-2; CCT5, chaperonin containing TCP1 subunit 5; GBAS, glioblastoma amplified sequence; RPS21, 40 S ribosomal protein S21." (PMID 30931934, 2019).
leukemia (1 paper, 2024). A malignant (clonal) hematologic disorder, involving hematopoietic stem cells and characterized by the presence of primitive or atypical myeloid or lymphoid cells in the bone marrow and the blood. "We first analysed the DA1-3b leukemia model and among the 70 commonly mutated genes in dormant leukemia DA1-3b/D365 and parental DA1-3b cells, ten genes (Ttc7b, Dnmt3b, Ap1b1, Ne1, Nedd4, Acy1, Cyp11a1, Htr2c, Magee1 and Gdi1) were amplified in dormant and parental cells." (PMID 39223638, 2024).
lung carcinoma (1 paper, 2026). "A systematic multi-omics analysis was conducted for the eight AP-1 adaptor complex genes (AP1AR, AP1B1, AP1G1, AP1G2, AP1M1, AP1M2, AP1S1, and AP1S3) to characterize their roles in lung cancer." (PMID 41438582, 2026). "While several AP-1 adaptor subunits, such as AP1B1 and AP1G1, have been studied in cancer 11, 12, a systematic evaluation of the AP-1 adaptor family in lung cancer is lacking." (PMID 41438582, 2026).
genetic disorders (3 papers, 2025 to 2026). "IDEDNIK syndrome is an extremely rare neurocutaneous genetic disorder resulting from pathogenic variants in AP1S1 or AP1B1, which encode subunits of the AP-1 complex." (PMID 41404470, 2025).
cancer (2 papers, 2021 to 2025). A tumor composed of atypical neoplastic, often pleomorphic cells that invade other tissues. "Other candidates, such as AP1B1, APOA1, YWHAH and YWHAZ, however, do not appear to be associated with docetaxel resistance in cancer." (PMID 34948097, 2021).
tumor (2 papers, 2024 to 2025).
infection (1 paper, 2025). The state of being infected such as from the introduction of a foreign agent such as serum, vaccine, antigenic substance or organism. "AP1B1 encodes lysosomal enzymes, and its expression was decreased in cattle during an infection with Johne’s disease (Mycobacterium avium subsp." (PMID 40379708, 2025).
AP1B1 also shares sentences with these, for which no sentence is quoted: myopia (2 papers); cervical squamous cell carcinoma (1); copper metabolism disorder (1); Epstein-Barr virus infection (1); gout (1); Hearing impairment (1); ichthyosis (1); keratitis (1); meningioma (1); neuropathy (1); ovarian carcinoma (1); peripheral neuropathy (1).